DENND2C (DENN domain containing 2C)
Description:
Guanine nucleotide exchange factor (GEF) which may activate RAB9A and RAB9B. Promotes the exchange of GDP to GTP, converting inactive GDP-bound Rab proteins into their active GTP-bound form.
Synonyms: FLJ37099; DKFZp686G0351; DKFZp779P1149; dJ1156J9.1; RP5-1156J9.1
Tractability: PROTAC: ubiquitination databases record sites on it.
Gene: Protein-coding gene on chromosome 1 (114,582,848 to 114,670,451, reverse strand). Ensembl gene ENSG00000175984.
Subcellular location (Human Protein Atlas): Nucleoplasm
Pathways (Reactome):
Vesicle-mediated transport: RAB GEFs exchange GTP for GDP on RABs
Gene Ontology:
Molecular function: guanyl-nucleotide exchange factor activity
Cellular component: nucleoplasm
Genetic constraint (gnomAD): Loss-of-function variants: 61 observed, 101.77 expected, observed/expected ratio (o/e) 0.6, 90% interval 0.49 to 0.74. The upper end of that interval is the gene's LOEUF score, 0.74, which puts it in group 3 of 6, group 1 being the genes least tolerant of losing a copy. Missense variants: 941 observed, 1,097.5 expected, observed/expected ratio (o/e) 0.86, 90% interval 0.81 to 0.9. Synonymous variants: 316 observed, 379.97 expected, observed/expected ratio (o/e) 0.83, 90% interval 0.76 to 0.91.
Homologues: Orthologues: chimpanzee DENND2C (99% identical), macaque DENND2C (98% identical), dog DENND2C (91% identical), pig DENND2C (91% identical), rabbit DENND2C (91% identical), guinea pig DENND2C (89% identical), mouse Dennd2c (83% identical), rat Dennd2c (83% identical), tropical clawed frog dennd2c (63% identical), zebrafish dennd2c (47% identical). Paralogues in human: DENND2A (48% identical), DENND2B (45% identical), DENND2D (23% identical).
Diseases named in the same sentence as DENND2C in open-access papers:
DENND2C is named in the same sentence as 3 diseases in open-access papers, as found by Europe PMC text mining. Sharing a sentence is not in itself a finding about the gene and the disease.
DENND2C shares sentences with these, for which no sentence is quoted: autism (1 paper); cancer (1); cystitis (1).